BECN1 (beclin 1)
Diseases named in the same sentence as BECN1 in open-access papers (continued):
Sharing a sentence is not in itself a finding about the gene and the disease.
melanoma (continued). "We performed western blot analysis to examine the expressions of autophagy-related proteins and the results showed that (+)-bornyl p-coumarate induced autophagy in melanoma cells, upregulating the protein levels of Beclin-1, LC3-I, LC3-II, Atg5, Atg3 and p62." (PMID 32466337, 2020). "In the present study, we found that SIRT1 promoted the EMT through deacetylation of Beclin 1 and autophagic degradation of E-cadherin in melanoma cells." (PMID 29374154, 2018). "Our data also suggest a previously unidentified link between the EGFR and Beclin-1 in melanoma cell line." (PMID 30100990, 2018). "In conclusion, the present study provides conclusive evidence that SIRT1 promotes the EMT by deacetylating Beclin 1 and then accelerates the autophagic degradation of the epithelial marker E-cadherin in melanoma cells." (PMID 29374154, 2018). "Our data suggest a previously unidentified link between the EGFR and Beclin-1 in melanoma cell line." (PMID 30100990, 2018). "Taken together, our data indicate that SIRT1 promotes E-cadherin degradation by autophagy through deacetylation of Beclin 1 in melanoma cells." (PMID 29374154, 2018). "Beclin-1 plays an important role in promoting the formation of autophagic vesicles during the cell autophagocytosis process in melanoma." (PMID 28532456, 2017). "To date, several markers of autophagy, including LC3 and Beclin 1, have been identified as potential prognostic biomarkers for melanoma." (PMID 27882308, 2016). "In the early phases of melanoma growth, mRNA and protein expression levels of the pro-autophagic proteins Beclin 1 and LC3 have been found to be lower compared to benign nevi." (PMID 27896217, 2016). "In A2058 human melanoma cells, the expression of Beclin 1 increased at 4 h incubation with the peptide." (PMID 27642552, 2016). "In contrast to normal melanocytes, ERK1/2 activation in melanoma cells induces the autophagic degradation of MITF via Beclin-1/ATG12/LC3-II upregulation, leading to the downregulation of TYR and tyrosinase-related proteins (TRP) 1/2 and ultimately suppressing melanin production." (PMID 40655947, 2025). "In models of mouse melanoma tumors, animals with Beclin-1 (+/−) showed a more aggressive tumor growth and increased angiogenic activity, compared to mice with Beclin-1 wild-type, by boosting the protein expression and stability of hypoxia-inducible factor-2α (HIF-2α)." (PMID 39650649, 2024). "Inhibition of melanoma autophagy through targeting at ATG5, p62/SQSTM1 and BECN1 activates MAPK8/JNK-JUN/c-Jun signaling pathway in melanoma cells which up-regulates CCL5 cytokine in the TME and thus enhance NK function via activation of NK cell activator NKp46." (PMID 36003368, 2022). "Furthermore, we showed that the infiltration of NK cells into Becn1 defective melanoma is increased, which results in significant inhibition of tumor growth." (PMID 33718194, 2021). "Abnormal expression of BECN1 has been found in human melanoma, colon, ovarian and brain cancers." (PMID 30696802, 2019). "We first examined the effect of SIRT1 on Beclin 1 acetylation in melanoma cells." (PMID 29374154, 2018). "The lysosomal inhibitor Baf A1 inhibited the production of MDC-positive vesicles induced by DDA and, in line with this, KD of the autophagic proteins ATG7, VPS34, and BECN1 in melanoma cells inhibited DDA-induced LC3-II formation, DDA-induced MDC-labeled punctates, and DDA-induced cell death." (PMID 29199269, 2017). "Likewise, Beclin 1 silencing in B16F10 melanoma halted tumor growth and increased apoptosis in vivo [further reviewed in Ref." (PMID 27896217, 2016). "In addition, studies of Beclin 1 expression suggest its’ downregulation parallels melanoma disease stage progression, further supporting a role for autophagy in tumor invasion and metastasis." (PMID 27882308, 2016). "Similarly elevated in explant melanoma cultures were Beclin-1 and LC3B expressions too." (PMID 33440911, 2021).
melanoma (continued). "SIRT1 also deacetylates Beclin 1, leading to upregulated autophagy and degradation of E-cadherin accompanied by increased metastatic potential of BRAF-mutant melanoma cells." (PMID 39935431, 2025). "Decursinol angelate is a coumarin compound that inhibits autophagy in melanoma B16-F10 cells by inhibiting ATG5, ATG7, and Beclin 1 expression and LC3-I to LC3-II conversion." (PMID 39371094, 2024). "Flavokawain B, a chalcone, induces ROS-mediated autophagy in melanoma A375 cells by inhibiting mTOR, increasing LC3-II levels, and dysregulating Beclin 1/Bcl-2 levels." (PMID 39371094, 2024). "Inhibition of the PI3K/Akt/mTOR pathway to enhance autophagy and overexpression of Beclin 1, LC3, and LC3-II are also observed in α-mangostin and polyphyllin I in melanoma cells." (PMID 39371094, 2024). "In regard to melanoma, the extensively studied potential autophagy-related biomarkers are LC3, p62, and Beclin-1." (PMID 39273093, 2024). "Immunohistochemical analysis of malignant melanomas has revealed an increased expression of LC3 and decreased expression of Beclin-1, which are correlated with poorer patient outcomes and the progression of metastasis." (PMID 39273093, 2024). "Metformin, an antidiabetic drug, induces autophagy in melanoma cells by regulating LC3 and Beclin 1 protein levels." (PMID 39371094, 2024). "In melanoma cells, Beclin-1 inhibition prevented Granzyme B degradation and increased NK cell infiltration in a CCL5-dependent manner, thereby inhibiting melanoma growth." (PMID 36009363, 2022). "We further investigated 2155–14-induced autophagy by western blotting of autophagy markers LC3-II and beclin-1 in both WM266–4 and M14 melanoma cells." (PMID 31573152, 2019). "Contrary to that, targeting Beclin-1 inhibits autophagy, overexpresses CCL5 and aids in recruit NK cells to the melanoma tumor." (PMID 29988591, 2018). "Aberrant expression of beclin-1 and LC3 has been documented in several solid tumors, including human colon cancer, melanoma, ovarian cancer, lung cancer and brain cancer." (PMID 23935917, 2013). "However, there are instances of Beclin-1 overexpression and LC3 downregulation in advanced melanoma." (PMID 39273093, 2024). "Interestingly, some autophagy markers (Beclin-1, Atg7) were also upregulated in MET-treated melanoma cells." (PMID 35216470, 2022). "The literature indicates that, like Beclin-1, other autophagy-related proteins, including Atg5, p62/SQSTM1 and chloroquine, which pharmacologically inhibits autophagy, also induce the expression of selected chemokines, e.g., CCL5 in melanoma cells." (PMID 34204085, 2021). "Moreover, Beclin-1, another core ATG protein involved in the initiation phase of autophagosome formation, was decreased in metastatic specimens compared to primary melanomas and benign nevi tissues." (PMID 34458153, 2021). "Moreover, the finding of significantly increased expression levels of the Atg5-12 complex and beclin-1 beginning after 24 h of incubation provided additional strong evidence supporting the hypothesis that IMQ combined with IR induced autophagy in mouse melanoma cells." (PMID 28212561, 2017). "Moreover, increased expressions of beclin-1, Atg3, Atg5, p62, LC3-I and LC3-II proteins and suppression by autophagic inhibitor 3-methyladenine (3-MA), indicated that (+)-bornyl p-coumarate triggered autophagy in the melanoma cells." (PMID 32466337, 2020). "Additionally, autophagy in melanoma A375 cells is induced by shikonin, a naphthoquinone isolated from Lithospermum erythrorhizon, and is involved in ROS-mediated ER stress, activation of p38 pathways, and upregulation of p-p38, LC3B-II, and Beclin 1 expression." (PMID 39371094, 2024). "In addition to BECN1 inhibition, targeting other autophagy-related molecules, such as ATG5 or p62/SQSTM1, or inhibiting melanoma autophagy pharmacologically by chloroquine can similarly induce the expression of CCL5 in melanoma cells and consequently enhance the antitumor capacity of NK cells." (PMID 36003368, 2022).
melanoma (continued). "However, our results showed that the resistance of melanoma to MitoX in vivo (but not in vitro) occurred due to tumor autophagic activity, since tumor autophagy inhibition by Becn1 silencing overcame chemoresistance to MitoX treatment and induced a tumor-suppressive immune microenvironment." (PMID 33809137, 2021).
Sepsis (58 papers, 2015 to 2025). Sepsis is defined as life-threatening organ dysfunction caused by a dysregulated host response to infection. "This study is the first to reveal potential activation of the entotic pathway in sepsis patients and identifies two key genes associated with this process: BECN1 and CYBB." (PMID 41346577, 2025). "In a rodent sepsis model, the TB-1 peptide improved cardiac function, reduced inflammation, and rescued phenotypes caused by Beclin 1 deficiency." (PMID 39596437, 2024). "On the other hand, genetic Beclin-1 deficiency resulted in aggravated sepsis-induced cardiac dysfunction." (PMID 32085438, 2020). "Beclin-1 protects mitochondria to reduce the release of mitochondrial danger-associated molecular patterns, and promotes mitophagy to decrease sepsis." (PMID 33324236, 2020). "Mice deficient for the autophagic protein Becn1 (Becn1+/−) were more likely to die from sepsis and be unresponsive to carbon monoxide therapy." (PMID 29201271, 2017). "The major constitutes of ginseng, ginsenoside Rg1, could assist mice against sepsis-associated encephalopathy by inducing Beclin-1 independent autophagy, resulting in promoting the survival rate." (PMID 30282915, 2018). "This indicates that rAAV9-Irf7 mediates sepsis protection in Irf7–/– mice via a mechanism that can be activated by BECN1." (PMID 41212050, 2025). "This study demonstrates the clinical efficacy of activating Beclin-1 to treat pneumonia-induced sepsis by modulating autophagy." (PMID 39200221, 2024). "In our study, Dex treatment reversed the increased expression of p-mTOR and reduced Beclin-1 levels induced by sepsis." (PMID 38419889, 2024). "In a rat model of sepsis, ghrelin administration was found to significantly upregulate the autophagy markers LC3, ATG7, and beclin-1 in small intestinal epithelial cells during early sepsis." (PMID 38275675, 2024). "Autophagy changes in response to sepsis severity, and Beclin 1 plays a key role in the autophagic response of the septic heart in a mouse model of LPS-induced sepsis." (PMID 37234771, 2023). "Our previous investigations suggest that promoting autophagy via Beclin-1 factor is beneficial for improving organ function, mitigating inflammation, and alleviating fibrosis in models of sepsis-induced cardiomyopathy." (PMID 36875088, 2023). "In our study, we found that the LC3II/LC3I ratio and Beclin 1 were significantly elevated in vivo and in vitro during sepsis." (PMID 35274595, 2022). "As shown, LAMP2, RAB7, LC3II, p62, and Beclin-1 predicted the AUC of death in sepsis patients with ARDS: 0.922, 0.833, 0.807, 0.745, and 0.708, respectively." (PMID 35371338, 2022). "The AUCs of LAMP2, p62, RAB7, LC3II, and Beclin-1 for the diagnosis of sepsis with ARDS are 0.853, 0.773, 0.746, 0.728, and 0.650, respectively." (PMID 35371338, 2022). "Recent studies have shown that specific overexpression of Beclin 1 can protect myocardial mitochondria and improve cardiac function in a mouse model of LPS-induced sepsis via the pink/parkin pathway." (PMID 35274595, 2022). "For instance, ABT-263, an inhibitor of the anti-apoptotic protein Bcl-2, enhances the bacterial phagocytosis of macrophages in aged mice by inducing beclin-1-dependent autophagy, which protects against sepsis." (PMID 36059534, 2022). "In conclusion, the autophagy level is significantly inhibited in sepsis patients with ARDS, and autophagy-associated proteins LC3II, Beclin-1, RAB7, LAMP2, and p62 have good value for the diagnosis and prognosis evaluation of sepsis patients with ARDS." (PMID 35371338, 2022). "Various autophagy-related mediators, such as LC3-11 and Beclin-1, are upregulated in sepsis-induced ALI." (PMID 33567713, 2021). "In conclusion, our study provides the evidence that ABT-263 enhanced the senescent macrophages function by increasing the Trem-2 receptors and inducing Beclin-1-dependent autophagy, consequently, improve the survival rate of sepsis on the aged mouse." (PMID 33794800, 2021).
Sepsis (continued). "In the studies summarized in this report, we evaluated the impact of Beclin-1–dependent autophagy on the outcomes after pneumonia-induced sepsis by both genetic and pharmacologic approaches." (PMID 34211859, 2021). "We detected that promoting Beclin-1–dependent autophagy has an anti-inflammatory effect in this model of pneumonia-induced sepsis, as shown by quantification of cytokine production and the evaluation of lung injury." (PMID 34211859, 2021). "LC3II and Beclin-1 levels in the liver tissues of mice in the CLP group decreased at 6 h post-sepsis, peaked at 12 h, and then decreased at 24 h." (PMID 33981237, 2021). "ABT-263 enhanced the macrophage function in aged mouse by increasing the Trem-2 receptors and inducing a beclin-1-dependent autophagy, consequently, protected the aged mouse from sepsis." (PMID 33794800, 2021). "Proteomic profiling of cardiac MAMs in models of sepsis with and without Beclin‐1 activation will provide a more profound understanding of the role of MAMs in sepsis‐induced cardiomyopathy and their potential regulation by Beclin‐1." (PMID 33733054, 2021). "The result suggests that Beclin-1 signal is at least essential for survival under the challenge of pneumonia-induced sepsis." (PMID 34211859, 2021). "Together, the data provide a strong support for the notion that Beclin-1–dependent autophagy presents therapeutic values to improve sepsis outcomes." (PMID 34211859, 2021). "In our experimental setting, we found that promoting Beclin-1–dependent autophagy significantly improved sepsis outcomes, including reductions in sickness scores, infection, and inflammation." (PMID 34211859, 2021). "Data suggest that targeted activation of Beclin-1 alleviates adverse outcomes of pneumonia-induced sepsis, and thus, possess a therapeutic potential." (PMID 34211859, 2021). "In sepsis-induced heart failure, cardiac-specific overexpression of Beclin-1 protected the mitochondria, ameliorated fibrosis, inflammation, and preserved cardiac function." (PMID 32085438, 2020). "Injection of the cell permeable Tat-Beclin-1 peptide has been shown to improve the cardiac function of sepsis mice." (PMID 33324236, 2020). "The Beclin 1 protein, a central regulator of autophagy in mammalian cells, has shown therapeutic effects for sepsis." (PMID 33324236, 2020). "Recent investigations suggest that specific activation of autophagy initiation factor Beclin-1 has a potential to protect cardiac mitochondria, attenuate inflammation, and improve cardiac function in sepsis." (PMID 30744190, 2019). "These manifestations of mitochondrial damage following LPS challenge were attenuated in the heart of mice with transgenic overexpression of Beclin-1, suggesting a critical function of Beclin-1 in the protection of cardiac mitochondria in sepsis." (PMID 30744190, 2019). "Since the activation of mTOR is inversely correlated with autophagic activities, the result suggests that enhancing Beclin-1 signaling can suppress mTOR activation, thereby sustaining autophagy even under conditions of severe sepsis." (PMID 30744190, 2019). "Beclin-1 mediated protection in sepsis was also suggested by a study of carbon monoxide therapy (CO) in the mouse CLP sepsis model." (PMID 30744190, 2019). "We inhibited autophagy by constructing MSCs with lentivirus containing small hairpin RNA to knockdown Beclin-1 and applied these MSCs to a model of sepsis to evaluate therapeutic effect of MSCs." (PMID 26670667, 2015). "Drug induction of autophagy via SIRT1-mediated Beclin-1 deacetylation may represent a promising therapeutic approach for sepsis treatment in the future." (PMID 40766066, 2025). "Similarly, in sepsis-induced cardiac insufficiency, relief can be observed through Sirt1-mediated Beclin-1 deacetylation and autophagy." (PMID 40766066, 2025).